SPTLC2 (serine palmitoyltransferase long chain base subunit 2)
Diseases named in the same sentence as SPTLC2 in open-access papers:
SPTLC2 is named in the same sentence as 46 diseases in open-access papers, as found by Europe PMC text mining. Sharing a sentence is not in itself a finding about the gene and the disease. The quoted sentences say what the papers report.
hereditary sensory and autonomic neuropathy type 1 (12 papers, 2013 to 2024). Hereditary sensory neuropathy type I (HSN I) is a slowly progressive neurological disorder characterized by prominent predominantly distal sensory loss, autonomic disturbances, autosomal dominant inheritance, and juvenile or adulthood disease onset. "Pathogenic variants in the cytoplasmic domains of SPTLC1 and SPTLC2 can cause hereditary sensory and autonomic neuropathy type 1 (HSAN1) and macular telangiectasia type 2 by abnormally increasing deoxy‐sphingolipid levels." (PMID 38316966, 2024). "Hereditary sensory and autonomic neuropathy type 1 is an autosomal dominant neuropathy caused by the SPTLC1 or SPTLC2 variants." (PMID 38927628, 2024). "Hereditary sensory neuropathy type 1 (HSN1) is caused by mutations in the SPTLC1 or SPTLC2 sub-units of the enzyme serine palmitoyltransferase, resulting in the production of toxic 1-deoxysphingolipid bases (DSBs)." (PMID 34337561, 2021). "Hereditary sensory neuropathy type 1 (HSN-1) is a peripheral neuropathy most frequently caused by mutations in the SPTLC1 or SPTLC2 genes, which code for two subunits of the enzyme serine palmitoyltransferase (SPT)." (PMID 29778900, 2018). "Hereditary sensory and autonomic neuropathy type 1 (HSAN1/HSN1) is a peripheral neuropathy most commonly associated with pathogenic variants in the serine palmitoyltransferase complex (SPTLC1, SPTLC2) genes, which are responsible for sphingolipid biosynthesis." (PMID 37107689, 2023).
Obesity (5 papers, 2022 to 2025). Accumulation of substantial excess body fat. "Heterozygous Sptlc2 knockout (KO) mice were protected from high-fat-diet-induced obesity, insulin resistance and atherosclerosis." (PMID 40998032, 2025). "It has been reported in the literature that ceramide production was reduced when SPTLC2 was knocked out specifically in the liver of mice, thereby effectively protecting them from high-fat diet-induced obesity." (PMID 40143173, 2025). "Smsr deficiency attenuates diet-induced obesity and MAFLD, which are reminiscent of SPTLC2 partial deficiency." (PMID 40998032, 2025). "The induction of obesity with the high-fat diet resulted in an increase in SPTLC2 expression in both subcutaneous (+203%) and visceral (+76.9%) adipose tissue compared to that of the control (p < 0.05)." (PMID 35628194, 2022). "Accordingly, deletion of Sptlc2 in UCP1-positive brown adipocytes protects mice from diet-induced obesity by increasing BAT function and systemic energy expenditure." (PMID 35789435, 2022).
diabetes (3 papers, 2023 to 2025). "In addition, PCOS is also closely associated with insulin resistance and is linked to an increased risk of developing type 2 diabetes; meanwhile, high ceramide levels have been consistently linked with insulin resistance and the development of diabetes, suggesting that SPTLC2 is the key hub in PCOS." (PMID 36695944, 2023). "In islets from patients with glucose intolerance or with diabetes secondary to pancreatic disease, SPTLC1 and SPTLC2 expression was not different from normogluco-tolerant patients." (PMID 40463068, 2025).
Insulin resistance (3 papers, 2017 to 2023). Increased resistance towards insulin, that is, diminished effectiveness of insulin in reducing blood glucose levels. "Taken together, these results indicated that ER stress upregulates Sptlc2 and increases the levels of ceramide, partly contributing to the development of hepatic insulin resistance." (PMID 35513574, 2022). "Currently, it is not clear whether this ER stress-mediated SPTLC2 induction process is a defensive mechanism to relieve chronic ER stress or a contributing factor for insulin resistance by excess lipids." (PMID 35513574, 2022).
type 2 diabetes (3 papers, 2017 to 2025). "Moreover, SPTLC2 mRNA tended to be lower, and SPTLC1 mRNA was significantly decreased, in islets from human subjects with type 2 diabetes versus normoglycemic individuals." (PMID 40463068, 2025).
atherosclerosis (2 papers, 2015 to 2025). A disease characterized by the build-up of fatty material and calcium deposition in the arterial wall resulting in partial or complete occlusion of the arterial lumen. "An interesting association between barrier defects and vascular inflammation in AD may be represented by the gene SPTLC2, which encodes a SPT, the rate-limiting enzyme in de novo synthesis of sphingomyelin and ceramides, and which has also been shown to influence atherosclerosis." (PMID 26459294, 2015).
frontotemporal dementia (2 papers, 2024 to 2025). Frontotemporal dementia (FTD) comprises a group of neurodegenerative disorders, characterized by progressive changes in behavior, executive dysfunction and language impairment, as a result of degeneration of the medial prefrontal and frontoinsular cortices. "Our study establishes SPTLC2 variants linked to early‐onset ALS with frontotemporal dementia (FTD), underscoring their pivotal role in the disease's pathology." (PMID 38316966, 2024). "Our study revealed novel SPTLC2 variants in patients with early‐onset ALS exhibiting frontotemporal dementia." (PMID 38316966, 2024). "Recently, it has been reported that variations in SPTLC2 are also associated with early-onset ALS and frontotemporal dementia (FTD)." (PMID 40271315, 2025).
Glucose intolerance (2 papers, 2022 to 2025). Glucose intolerance (GI) can be defined as dysglycemia that comprises both prediabetes and diabetes. "Pharmacological and genetic inhibition of de novo ceramide biosynthesis improved glucose intolerance in diet-induced obese (DIO) or heterozygous Sptlc2-deficient mice." (PMID 35513574, 2022).
Hepatic steatosis (2 papers, 2018 to 2025). Steatosis is a term used to denote lipid accumulation within hepatocytes. "In addition, the adipocyte-specific SPTLC2-knockout mice also accompanied hepatic steatosis, implying a mirror image phenotype of lipid deposition and content as the Ipra-treated mice in our study." (PMID 30382157, 2018).
hereditary sensory and autonomic neuropathy (2 papers, 2018 to 2024). An instance of sensory peripheral neuropathy that is caused by an inherited modification of the individual's genome. "Our studies indicate that SPTLC2 variant [c.778G>A, p.Glu260Lys] acts distinctly from hereditary sensory and autonomic neuropathy (HSAN)-causing SPTLC2 variants by causing excess canonical sphingolipid biosynthesis, similar to the recently reported SPTLC1 ALS associated pathogenic variants." (PMID 38041679, 2024). "A total of 75 patients with CMT (including 21 with hereditary sensory neuropathy due to mutations in SPTLC1 and SPTLC2) and 67 healthy controls were enrolled into the study." (PMID 29321234, 2018).
psoriasis (2 papers, 2022 to 2023). An autoimmune condition characterized by red, well-delineated plaques with silvery scales that are usually on the extensor surfaces and scalp. "For example, in psoriasis lesional skin, SPTLC2 was upregulated and SPTLC3 was downregulated, which would increase the synthesis of ceramides with 18-carbon sphingoid bases and decrease the synthesis of ceramides with long-chain sphingoid bases." (PMID 35900871, 2022). "For example, the ceramide abundances in psoriasis lesional skin matched the increased expression of CERS3 and SPTLC2 and the decreased expression CERS6." (PMID 35900871, 2022).
Sepsis (2 papers, 2023 to 2024). Sepsis is defined as life-threatening organ dysfunction caused by a dysregulated host response to infection. "For example, inhibition of Sptlc2-dependent sphinganine production would decrease sepsis-associated inflammation." (PMID 39025856, 2024). "Collectively, these results suggested that Sptlc2 deficiency decreases LPS-induced inflammation in vivo and ameliorates sepsis symptoms through attenuating MyD88-directed signal transduction." (PMID 39025856, 2024). "Among them, the AUCs of ITGAM, KIF1B, RRAGD, S100A9, SCOC, and SPTLC2 in the internal and external test sets were more than 0.6, indicating diagnostic significance for sepsis." (PMID 37834169, 2023). "Beyond the sepsis model, we used a B16 melanoma mouse model to test the role of Sptlc2 in regulating macrophage function in vivo." (PMID 39025856, 2024). "We explored the impact of Sptlc2 deletion in a polymicrobial sepsis model using intraperitoneal cecal slurry injections." (PMID 39025856, 2024). "Similar as the LPS-induced sepsis model, cecal slurry injection increased Sptlc2 levels and Lyz2-cre mice exhibited an impaired M1-like and enhanced M2-like macrophage phenotype." (PMID 39025856, 2024). "To test whether Sptlc2 might be required for LPS-induced inflammatory responses in vivo, we used an LPS-induced sepsis mouse model." (PMID 39025856, 2024).
atopic dermatitis (1 paper, 2025). "Through systematic computational analysis, this study untangles the core molecular network (SPTLC2, AMD1, IGSF3) and the key metal metabolic regulatory axis (copper homeostasis pathway) involved in the pathophysiology of atopic dermatitis (AD)." (PMID 40564068, 2025).
Chronic colitis (1 paper, 2018). A chronic inflammatory disease of the large intestine (colon, cecum and rectum). "Importantly, intestine-specific Sptlc2-deficient mice can mimic certain phenotypes observed in human inflammatory bowel diseases, such as Crohn’s disease, chronic colitis, and ulcerative colitis." (PMID 29415989, 2018).
colon cancer (1 paper, 2021). "Further, among validated DEGs were those with established roles in colon cancer and CCSC (KLF6 and SQSTM1) and those with emerging roles (SPTLC2, SEC24D, and ACACA)." (PMID 34845203, 2021).
Crohn disease (1 paper, 2018). A gastrointestinal disorder characterized by chronic inflammation involving all layers of the intestinal wall, noncaseating granulomas affecting the intestinal wall and regional lymph nodes, and transmural fibrosis. "Moreover, all diseased colons expressed less SPTLC2 mRNA, although this difference was not statistically significant for Crohn’s disease." (PMID 29415989, 2018).
Ewing sarcoma (1 paper, 2023). A small round cell tumor that lacks morphologic, immunohistochemical, and electron microscopic evidence of neuroectodermal differentiation. "In addition, we found that another gene, SPTLC2, was associated with both mepacrine and the human Ewing's sarcoma cell line, A673." (PMID 37072452, 2023). "Therefore, SPTLC2 may be a novel mepacrine target for treating human Ewing’s sarcoma." (PMID 37072452, 2023).
fungal infection (1 paper, 2015). "To investigate the role of sphingolipid biosynthesis in the production of cytokines upon fungal infection, we used zymosan to stimulate Sptlc2-/- and control DC2.4 cells." (PMID 26431038, 2015). "This corroborates our in vitro observations and underscores the importance of sphingolipid homeostasis in clearing fungal infections; (vi) lipidomic analysis is entirely consistent with the specificity of the inhibitors used and with the genetic defect in Sptlc2-/- DC2.4 cells." (PMID 26431038, 2015).
hereditary sensory and autonomic neuropathy types IA (1 paper, 2022). "Mutations in STPLC1 and SPTLC2 have been associated with hereditary sensory and autonomic neuropathy types IA and IC (HSAN1A and HSAN1C), respectively." (PMID 36061210, 2022).
ichthyosis (1 paper, 2019). Disorders of cornification that are characterized by visible scaling and/or hyperkeratosis of most or all of the skin. "In line with this, the expression of SPTLC2 and SMPD1 and seven ichthyosis‐causing genes involved in the pathway of acylCer and CLE formation was induced in the range of 2‐4 times." (PMID 30372788, 2019).
inflammatory bowel disease (1 paper, 2018). A spectrum of small and large bowel inflammatory diseases of unknown etiology. "We also found that colon specimens from patients with inflammatory bowel diseases had significantly reduced Sptlc2 expression, SPTLC2 staining, and goblet cell numbers." (PMID 29415989, 2018).
motor neuron disease (1 paper, 2024). "SPTLC2 is the second SPT-associated gene that underlies monogenic, juvenile ALS and further establishes alterations of sphingolipid metabolism in motor neuron disease pathogenesis." (PMID 38041679, 2024).
neuropathy (1 paper, 2021). A disorder affecting the nervous system that manifests with pain, tingling, numbness, and/or muscle weakness. "Furthermore, heterozygous SPTLC1- and SPTLC2-knockout mice exhibit a reduction in SPT activity; however, no neuropathy was documented, again arguing against haplotype insufficiency and for toxic gain of function as the cause of the neuropathology." (PMID 34337561, 2021).
renal cell carcinoma (1 paper, 2021). "The role of SPTLC2 in cancer stem cells is unexamined, but its lowered expression in renal cell carcinoma leads to poor patient survival." (PMID 34845203, 2021).
infection (6 papers, 2015 to 2023). The state of being infected such as from the introduction of a foreign agent such as serum, vaccine, antigenic substance or organism. "Research on mice has shown that adenovirus AdSptlc2 (an adenovirus containing SPTLC2) infection leads to the downregulation of gluconeogenic genes, resulting in a decrease in plasma glucose levels." (PMID 37968610, 2023). "Similar to infections with Mtb, Sptlc2−/− RAW264.7 and DC2.4 cells showed an ∼50% reduction in phagocytic uptake of M. marinum relative to wild-type cells." (PMID 33500344, 2021). "To determine at which step in this process sphingolipids exert their critical role, we monitored F-actin dynamics in wild-type and Sptlc2−/− RAW264.7 cells expressing LifeAct-mKate during infection with a monomeric GFP (mGFP)-expressing strain of M. marinum." (PMID 33500344, 2021).
tumor (5 papers, 2020 to 2025). "CERS6 and SPTLC2 were classified into a high-risk group with higher hazard ratios (HR > 1) and higher expression in tumor tissues, but S1PR1 exhibited a protective effect (HR < 1) and lower expression in malignant tissues." (PMID 40057751, 2025). "RT-qPCR of both in vitro and in vivo tumor cells also revealed significant up-regulation of key enzymes involved in glycosphingolipid biosynthesis, including St3gal1, St3gal2, B4galt5, Sptlc2, and Ugcg, in A159V-mutated cells." (PMID 41160695, 2025). "Furthermore, tumor-associated macrophages (TAMs) expressed higher levels of Sptlc2 protein than splenic macrophages in a B16-F10 tumor model." (PMID 39025856, 2024). "Furthermore, TLR4-independent pathways, which are induced or inhibited through Sptlc2 deficiency, might potentially have contributed to the phenotype of the tumor model." (PMID 39025856, 2024). "Collectively, these results suggested that Sptlc2 is required for monocyte and macrophage-mediated anti-tumor responses." (PMID 39025856, 2024). "Perhaps, the high expression of SPTLC2 is closely related to the development of tumors, and it is very likely to become one of the markers for auxiliary tumor examination." (PMID 36438896, 2022). "Sptlc2 deficiency did not impact splenocyte or tumor-infiltrating leukocyte numbers but increased the tumor growth longitudinally and the tumor weight at the endpoint." (PMID 39025856, 2024). "SPTLC2 is likely to be a new target for tumor inhibition via sphingolipid-related pathways." (PMID 36438896, 2022). "SPTLC2 is a promising target for tumor inhibition in the future." (PMID 36438896, 2022). "In conclusion, SPTLC2 may be associated with the antivascular and antitumor effects of TP, and SPTLC2 is expected to become a new marker for tumor therapy." (PMID 36438896, 2022). "Sptlc2 is one of the major SPT subunits and was upregulated in hepatocytes, cholangiocytes, and immune cells in both pre-tumor and HCC groups." (PMID 40057751, 2025).
neurodegenerative disease (2 papers, 2023 to 2024). A disorder of the central nervous system characterized by gradual and progressive loss of neural tissue and neurologic function. "Alterations of the SPT activity caused by mutations of either SPTLC1 or SPTLC2 gene are linked to neurodegenerative diseases such as hereditary sensory and autonomic neuropathy type I (HSAN1) in human." (PMID 37030501, 2023). "Human SPT is a membrane-bound large protein complex containing SPTLC1/SPTLC2 heterodimer as the core subunits, and it is known that mutations of the SPTLC1/SPTLC2 genes increase the formation of deoxy-type of LCBs derived from l-Ala and Gly to cause some neurodegenerative diseases." (PMID 37030501, 2023). "Recognition of ALS, including its sporadic forms, as a broader neurodegenerative disease with a predilection for frontal and temporal lobes is thus consistent with our findings in SPTLC2 E260K ALS." (PMID 38041679, 2024).
neurological diseases (2 papers, 2023 to 2024). "The main overlapping gene between YT and CT, SPTLC2, is located on BTA10 and is associated with neurological diseases in humans and re-learning mechanisms in rats." (PMID 36658485, 2023). "Apart from the SPTLC2 variant, the remaining candidate de novo variants were found in public population databases (gnomAD and ToMMo [jMorp, 38KJPN]) and lacked any reported association with neurological diseases." (PMID 38316966, 2024).
inflammation (1 paper, 2020). Aberrant reaction of the microcirculation characterized by movement of fluid and leukocytes from the blood into extravascular tissues. "Collectively, increased SPTLC2 may contribute to eosinophilic airway inflammation and lung dysfunction." (PMID 33031402, 2020).
metabolic disease (1 paper, 2024). A congenital disorder (due to inherited enzyme abnormality) or acquired (due to failure of a metabolically important organ) disorder resulting from an abnormal metabolic process. "Additionally, only in male NASH patients, there was a significant increase in expression of SPTLC2, a subunit of SPT, that regulates its activity and de novo ceramide biosynthesis and contributes to metabolic diseases." (PMID 38081412, 2024).
SPTLC2 also shares sentences with these, for which no sentence is quoted: peripheral neuropathy (5 papers); cancer (3); amyotrophic lateral sclerosis (2); macular telangiectasia type 2 (2); schizophrenia (2); sensory neuropathies (2); dermatitis (1); influenza (1); juvenile amyotrophic lateral sclerosis (1); lipodystrophy (1); melanoma (1); motor neuron degeneration (1); myocardial infarction (1); pancreatic disease (1); psychiatric diseases (1); ulcerative colitis (1).